FN1 (fibronectin 1)
Diseases named in the same sentence as FN1 in open-access papers (continued):
Sharing a sentence is not in itself a finding about the gene and the disease.
renal fibrosis (150 papers, 2013 to 2026). A final common manifestation of a wide variety of chronic kidney diseases characterized by glomerulosclerosis and tubulointerstitial fibrosis. "Last, the lesser inflammation was associated with lower renal fibrosis and expression of profibrotic genes (Col1a1, Col3a1, Fn1, and Vim) in UUO kidney of Casp9 HZ mice." (PMID 34739325, 2021). "In addition to TGF-β, other key indicators of renal fibrosis include Col1a1 expression, which encodes the alpha-1 chain of type 1 collagen; Fn1, which encodes fibronectin 1; and Acta2, which encodes smooth muscle α-actin, α-SMA." (PMID 41516371, 2026). "scRNA-seq revealed that empagliflozin modulated the TGF-β signaling pathway, inhibited intercellular communication, and reduced the expression of fibrotic genes such as Col4a1 or Fn1 that are associated with miR-192-mediated TGF-beta/SMAD3-driven renal fibrosis." (PMID 41303298, 2025). "Confirming our dose range experiments, X203 reduced AKI-induced loss of kidney mass, limited renal fibrosis, and improved renal function while lowering inflammatory (Tnfα, Il6, Ccl2, Ccl5, Il1β), fibrosis (Col1a1, Col1a2, Col3a1, Fn1, Acta2) and tubular damage (Kim1, Ngal) markers." (PMID 36470928, 2022). "LIPUS drastically downregulated the mRNA levels of renal fibrosis markers, such as Tgfb1, Serpine1, Fn1, and Acta2." (PMID 40729113, 2025). "Transforming growth factor β1 (TGF-β1), monocyte chemoattractant protein-1 (MCP-1) expression, alpha-smooth muscle actin (α-SMA), collagen type I (COL1/collagen I), and fibronectin-1 (FN1) constitute pivotal factors in renal fibrosis." (PMID 40870466, 2025). "And, knockout of ISG15 led to decreased TGFβR1 and its downstream p-Smad2 levels, reduces transcription levels of fibrotic genes such as α-SMA, Fn1, and Vimentin, ultimately inhibited renal fibrosis." (PMID 39113797, 2024). "The elevated expression of fibrotic markers, specifically TGF-β1, FN-1, and SMα, also establishes a connection between hypercalciuria, alkalinuria, and renal fibrosis." (PMID 38732005, 2024). "In renal fibrosis, the hallmark of CKD, it is known that Col 1, 2, 3, 5, 6, 7 and 15, Fn1, Dcn and Bgn accumulate in the ECM." (PMID 36769148, 2023). "Q-PCR indicated a significant reduction in the expression of renal fibrosis-related genes (fn-1, αSMA, Col1a1, Col3a1, Ctgf, fsp1, KIM) and inflammatory cytokines (Tgfα, Tgfβ, Il-1b, Il-4, Il-6, CD44, CD68) in the kidney of the acetate-treatment group." (PMID 36922584, 2023). "Intriguingly, Ly6C+ and Arg1+ myeloid cells also exhibited elevated levels of Fn1 and Vim in comparison to resident macrophages, suggesting a potential role of myeloid glycolysis in renal fibrosis initiation." (PMID 38035106, 2023). "Results from Western blot also showed a reduction in the expression of renal fibrosis-related proteins (αSMA, Fn-1, Col3a1) and inflammatory factors (IL-1β, IL-6, TGF-β) in the kidney of acetate-treatment group." (PMID 36922584, 2023). "Measurement of mRNA levels of Col3a1 and Fn1, assessment of renal fibrosis by Masson’s trichrome staining, and quantification of α-SMA-positive areas revealed a marked decrease of fibrosis in kidneys treated with Bex." (PMID 36443310, 2022). "The degree of renal fibrosis, assessed through expression of Fibronectin-1, and the expression of proinflammatory IL-1β were greater, and the expression of glucose transporter GLUT4 was lower in DN compared to control mice." (PMID 34221188, 2021). "At the same time, expression of inflammatory cytokines (Il1b, Csf2, Tnfa, and Cxcl10), renal fibrosis, and profibrotic genes (Col1a1, Col3a1, Fn1, and Vim) was lower in the FA-treated Casp9 HZ mice." (PMID 34739325, 2021). "In contrast, in Klf5+/– UUO‐mice, the expression of fn1 and tgfβ1 gene which encode for FN and TGF‐β were increased concurrent with increased renal fibrosis as compared to UUO‐WT mice." (PMID 33523554, 2021).
renal fibrosis (continued). "The downstream target genes of the Wnt canonical pathway are all involved in renal fibrosis, including fibronectin 1 (FN1), Cluster of differentiation 44 (Cd44), fibroblast specific protein-1 (FSP-1), and matrix metalloproteinase-7 (MMP-7)." (PMID 35059392, 2021). "Expression of Fibronectin-1 in the kidney in the DN mice was significantly elevated, and the inflammatory factor IL-1β increased, thus suggesting an increase in renal fibrosis and inflammation in the DN mice model." (PMID 34221188, 2021). "It is known that FN1 is an accumulation constituent of the extracellular matrix in the case of hyperglycemia and plays an essential role in renal fibrosis." (PMID 34424825, 2021). "The genes FN1, and PTPRO were reported by the Online Mendelian Inheritance in Man (OMIM) database to be associated with glomerulopathy, renal fibrosis and nephrotic syndrome, respectively." (PMID 34557161, 2021). "Mutation of the FN1 gene can lead to glomerular disease with fibronectin deposition (GFND), and the expression of FN1 is increased in renal fibrosis." (PMID 35059432, 2021). "The miRNA-mediated inhibition of E-Box repressors (e.g., Zeb1) of upstream flanking region of fibrotic genes (such as Fn1 and Collagens) under chronic Tgfβ signaling has been demonstrated to drive renal fibrosis." (PMID 23326503, 2013). "Similarly, 14 days after UUO, the kidneys of MΦ atg5−/− mice revealed less renal fibrosis, as indicated using quantitative SR and Masson staining, and reduced staining for fibrotic components (FN1, vimentin, and α-SMA) compared to WT littermate mice." (PMID 38594728, 2024). "A recent study showed that CREB lncRNA targeted CREB5 to regulate FN1 in renal fibrosis." (PMID 37176063, 2023). "Similarly, renal fibrosis was increased in all kl/kl mice and mRNA expression of markers of fibrogenesis such as Timp1, Col1a2 and Fn1 were elevated in kl/kl kidneys independently of the presence of FGFR4." (PMID 31575945, 2019). "Furthermore, the mRNA expression of the renal fibrosis-related genes Col1a2, Fn1, and Tgfb1 were all significantly increased in Pkd1 miR Tg mice (p < 0.05) compared with wild-type mice." (PMID 30585217, 2018). "However, the expression of ECM genes such as mesenchymal collagens Col3a1 and Col1a1 as well as EMT markers found in tumorigenic EMT or renal fibrosis, including EMT-associated cytoskeleton Vimentin, Fn1 and Sparc, were significantly increased in Smarca4cKO tubular cells." (PMID 37727504, 2023). "Fibronectin 1 (FN1) and matrix metalloproteinase 9 (MMP9) were the typical extracellular matrix (ECM) and pathological biomarkers of renal fibrosis." (PMID 40417738, 2025). "Immunohistochemical staining for fibrotic components showed lower levels of FN1, vimentin, and α-SMA in the kidneys of MΦ atg5−/− mice than in those of WT littermate mice, indicating reduced severity of renal fibrosis." (PMID 38594728, 2024). "At day 7 post-UUO surgery, the extent of renal fibrosis was induced in Sirt2tKO kidneys; they displayed higher levels of CTGF, FN1, COL3A1, and α-SMA compared to WT mice after UUO surgery." (PMID 37777567, 2023). "FN1 is identified as the principal component of ECM, and elevated FN1 levels reflect more severe renal fibrosis in IgAN." (PMID 36978098, 2023). "The injection of an miR−122−5p mimic promoted renal fibrosis and upregulated COL1A2 and FN1, whereas an miR−122−5p inhibitor suppressed renal fibrosis and downregulated COL1A2 and FN1." (PMID 36499744, 2022). "Next, we evaluated the expression of three genes that are increased in renal fibrosis [collagen 1A2 (COL1A2), fibronectin 1 (FN1), and α-smooth muscle actin (α-SMA)]." (PMID 36499744, 2022). "Among the LLC1-derived nephrotoxic secretory proteins, ANGPL2, BMP-1, DCN, FN1, and MCP-1 have been shown to contribute to TGF-β signaling-dependent renal fibrosis." (PMID 33260558, 2020).
renal fibrosis (continued). "Our study found that under chronic hypoxia, mitophagy activation effectively inhibited the expression of Vimentin, α-SMA, Collagen I, and FN1, suggesting that mitophagy may play a protective role in EMT progression and renal fibrosis." (PMID 40305351, 2025). "EZP and EYP inhibited the gene expression of FN1 and MMP9 in a renal fibrosis cell model." (PMID 40417738, 2025). "Overexpression of lncRNA PVT1 induced by hyperglycemic conditions promotes the expression of primary components of glomerular ECM, including plasminogen activator inhibitor 1, and TGF-β1, FN1 in mesangial cells, thus indicating the positive role of PVT1 in renal fibrosis." (PMID 32752143, 2020). "Moreover, RNA-seq analysis revealed that the SVF-treated group exhibited significantly reduced expression levels of Fn1, Col1a2, and Acta2, suggesting that SVF may attenuate renal fibrosis progression." (PMID 40432888, 2025). "To unravel the physiological roles of PPM1K in renal fibrosis, we analyzed the RNA-sequencing dataset of a PPM1K-overexpressing HK2 cell line (GSE212681) and identified reduced expression of fibrosis-related genes such as Col1A1, Col2A1, CTGF, vimentin, and FN1 (Fig. EV3)." (PMID 40588562, 2025). "Besides, co-culturing with ITGB3-overexpressed cells could upregulate COL1 and FN1 expression in HK-2 cells, whereas SB525334 could reduce that, suggesting that ITGB3 might induce renal fibrosis related to senescence." (PMID 34805144, 2021). "In another study, it was noted that renal fibronectin-1 (FN-1) gene expression in type 1 diabetic mice was augmented by the enrichment of H3K9/14Ac and HAT p300/CBP at the promoters of the FN-1 gene, which would lead to the development of renal fibrosis and expression of DKD." (PMID 28695133, 2017).
ovarian carcinoma (94 papers, 2007 to 2026). A malignant neoplasm originating from the surface ovarian epithelium. "Utilizing the word cloud, we identified morphogenesis as the most relevant pathway associated with C3 FN1+ TCs, indicating its involvement in the early development of ovarian cancer." (PMID 40612060, 2025). "The study involved two groups: high and low FTRS (FN1+ TCs Risk Score) groups, aimed at investigating the influence of FN1 high-expressing TCs on ovarian cancer patients, utilizing the 10 prognostic mRNAs identified from the TCGA cohort." (PMID 40612060, 2025). "A comparable study indicated that FN1, the gene associated with C3 FN1+ TCs, served as a marker correlated with unfavorable outcomes, while another investigation revealed its involvement in regulating the advancement of ovarian cancer." (PMID 40612060, 2025). "Actually, it has been reported that FN1 can prevent the apoptosis of ovarian cancer cells caused by therapeutic agents." (PMID 34093898, 2021). "Degradation or alteration of FN1 expression has been associated with cancer progression, such as in squamous cell carcinoma, nasopharyngeal carcinoma, ovarian cancer, and renal cancer." (PMID 33738254, 2021). "FN1 was previously reported to be associated with adverse or poor prognosis of breast and ovarian cancer." (PMID 32315343, 2020). "Recently, it has been shown that SOX2, a gene encoding a transcription factor that targets FN1, is a key gene regulating cell migration in ovarian cancer." (PMID 24676469, 2014). "Similarly, Yoshiharaet al. showed that ovarian-associated mesothelial cells induce and activate the FN1/Akt signaling pathway, thereby promoting the resistance of ovarian cancer peritoneal metastases to DDP." (PMID 38477044, 2024). "Similarly, up-regulation of COL3A1 and FN1 has been linked to unfavorable OS in stomach and ovarian cancers, respectively." (PMID 38913913, 2024). "Moreover, activation of the Akt signalling pathway induced by FN1 interactions has been associated with platinum resistance in ovarian cancer cells in direct contact with cancer-associated mesothelial cells." (PMID 37686015, 2023). "Numerous studies have shown that elevated FN1 expression is associated with the development and progression of various cancer types, including head and neck squamous cell carcinoma, hepatocellular cancer, thyroid cancer, gastric cancer, ovarian cancer and renal cancer." (PMID 40860666, 2025). "Ovarian cancer cell and mesothelial cell crosstalk promotes tumor adhesion and invasion, but ovarian-cancer-associated mesothelial cells also induce chemoresistance through the ATP-binding cassette transporter protein induction of the fibronectin 1/Akt signaling pathway." (PMID 36984544, 2023). "Moreover, FN1 was found to be able to avoid the apoptotic activities of ovarian cancer cells caused by therapeutic agents, implying that the regulation of FN1 may improve the therapeutic effect." (PMID 31304688, 2019). "This signature features known disease drivers and oncogenic ECM proteins associated with ovarian cancer progression and metastasis (e.g., NNMT, CD163, and FN1) and sheds light on proteins with high therapeutic potential." (PMID 41233595, 2026). "According to a study of platinum resistant ovarian cancer, peritoneal mesothelial cells, which experience EMT process, can activated ovarian cancer cells’ AKT pathway by FN1 expression on mesothelial cells, inducing to platinum resistance." (PMID 39968688, 2025). "The amplification of JUNB was associated with a worse outcome in ovarian cancer patients, while the gene MSLN, prevalent in C3 FN1+ TCs, was previously thought to have a role in the peritoneal dissemination of ovarian TCs." (PMID 40612060, 2025). "Additional research was required to comprehensively elucidate the impact of FN1 signaling molecules on ovarian cancer development." (PMID 40612060, 2025).
ovarian carcinoma (continued). "The results of SlingShot’s analysis aligned with Monocle’s findings, indicating that omental tissue and C3 FN1+ TCs subtypes were likely origins of ovarian cancer formation." (PMID 40612060, 2025). "The study highlighted FN1 expression as a key factor in ovarian cancer prognosis and immune resistance." (PMID 40612060, 2025). "A prognostic model created based on FN1 tumor cells provided a new idea for clinical staging of ovarian cancer patients." (PMID 40612060, 2025). "Our findings suggested that FN1+ tumor cells contributed to immunotherapy resistance, making FN1 a potential biomarker and therapeutic target for improving treatment outcomes in ovarian cancer." (PMID 40612060, 2025). "When they cocultured the mesothelial cells which was induced to experience EMT process by TGF‐βhand the ovarian cancer cells, by blocking FN1 expression, they proved that mesothelial cells activating cancer cells AKT pathway leading to platinum resistance." (PMID 39968688, 2025). "FAK also plays an important role in the regulation of cell migration, invasion, adhesion, proliferation, and viability in ovarian cancer, and FN1 is involved in the upregulation of the FAK pathway to stimulate ovarian cancer cell migration and invasion." (PMID 38338902, 2024). "FN1 is involved in the EMT and metastasis of OC and confers platinum-resistant ovarian cancer-associated mesothelial cells." (PMID 38814534, 2024). "It is known that soluble FN1 is detectable in ascitic fluid and also that endogenous FN1 is secreted by ovarian cancer cells." (PMID 35055018, 2022). "MiR-101 is discovered to repress cell metastasis of ovarian cancer via decreasing Fibronectin 1(FN1) expression." (PMID 36497343, 2022). "High expression of FN1 was observed in cervical cancer, hepatocellular carcinoma, ovarian cancer, and esophageal cancer." (PMID 36035176, 2022). "In a previous study, the expression of fibronectin 1 was found to be high in the advanced stages of ovarian cancer 34093898." (PMID 35741311, 2022). "Numerous studies have shown that FN1 in oral squamous cell carcinoma, ovarian carcinoma, nasopharyngeal carcinoma is differentially expressed and demonstrates distinct functions in cancer proliferation, migration, and invasion." (PMID 36081567, 2022). "Another study showed that SOX2 is a transcription factor of FN1 that promotes the migration and invasion of ovarian cancer cells." (PMID 36601474, 2022). "Online clinical data also showed that ovarian cancer patients had high FN1 expression levels compared with normal people." (PMID 35370699, 2022). "The role of endogenous FN1 in metastasis has been previously demonstrated in experimental models of ovarian cancers." (PMID 35055018, 2022). "Previous studies demonstrated that FN1 was related to the invasion and migration of ovarian cancer cells." (PMID 35370699, 2022). "In a variety of tumors, such as nasopharyngeal carcinoma, osteosarcoma, esophageal cancer, and ovarian cancer, FN1 is an important tumor-related gene." (PMID 34093898, 2021). "In our study, online database analysis (Oncomine) was used to examine the expression levels in patients, and ovarian cancer patients were found to have higher FN1 expression levels than normal subjects." (PMID 34093898, 2021). "Studies have shown that the expression of FN1 protein is closely related to the occurrence and development of many types of malignant tumors, such as ovarian cancer, renal cell carcinoma, and thyroid cancer." (PMID 34229299, 2021). "Based on the Oncomine database analysis, comparing with normal people, ovarian cancer patients exhibited high levels of FN1 expression." (PMID 34093898, 2021). "Comparing the four different ovarian cancer cells, high FN1 expression was found in OVCAR3 at mRNA level, protein level, and the cell medium level." (PMID 34093898, 2021). "Based on these results, FN1 should be a very important protein for the migration and invasion abilities of the ovarian cancer cells." (PMID 34093898, 2021).